PARP1 (poly(ADP-ribose) polymerase 1)
Diseases named in the same sentence as PARP1 in open-access papers (continued):
Sharing a sentence is not in itself a finding about the gene and the disease.
cancer (continued). "As PARP-1 inhibitors are currently being used clinically as anti-cancer therapies, characterizing the cellular role of PARP-1 is crucial for understanding the therapeutic potential of these agents." (PMID 23104860, 2012). "The different roles of PARP1 in processes other than HRR have also been investigated in order to find synthetic lethal interactions that can be exploited for new cancer therapies." (PMID 24970153, 2012). "On the other hand, small alkylating agents have been shown to be able to kill cancer cells resistant to apoptosis by a process known as "programmed necrosis" through depletion of NAD+ via PARP1 activation." (PMID 21303518, 2011). "Tolerability and efficacy of PARP1 inhibitor Olaparib in cancer treatment has now been confirmed in adult phase I and II clinical trials." (PMID 22184287, 2011). "The present study thus demonstrates the potential of combined inhibition of PARP-1 and telomerase for cancer therapy." (PMID 20678253, 2010). "Our finding is in accordance with earlier studies showing increased expression of PARP-1 in cancer, as described in the Introduction section." (PMID 19568233, 2009). "The mean activity in the cancer cells was 45-fold higher than the mean activity in normal human lymphocytes and the PARP-1 protein levels were 23-fold higher." (PMID 19568233, 2009). "In contrast to the proposed role of PARP-1 activity in inhibiting cancer development, PARP expression and/or activity is generally higher in cancer tissue compared with normal tissue." (PMID 19568233, 2009). "Overall, our data show significant upregulation (approximately 23-fold higher) of PARP-1 expression in the cancer cell lines compared with human lymphocytes from healthy volunteers and cancer patients." (PMID 19568233, 2009). "Our study is the first investigation of a role for the CA microsatellite in PARP-1 expression in cancer cells." (PMID 19568233, 2009). "Poly(ADP-ribose) polymerase-1 clearly has the potential to inhibit the development of cancer, by promoting genomic stability through DNA repair and cell-cycle control." (PMID 19568233, 2009). "BPA may promote cervical carcinogenesis by interacting with ESR1 and PARP1 to regulate key cancer-related pathways." (PMID 41790626, 2026). "Because the increase in MMEJ depends on HR, we did not expect PARP1/2 inhibition to modulate MMEJ in HR-deficient cancer cells." (PMID 41495903, 2026). "Although increased clearance of trapped PARP1 from chromatin reduces the sensitivity of cancer cells to PARPi, details surrounding this process remain unclear." (PMID 42230924, 2026). "The pronounced reduction in the full-length PARP1 band that we observed provides compelling evidence that the treatment successfully induced caspase activation and overcame the anti-apoptotic defensive response typical of cancer cells." (PMID 41596301, 2026). "Cancers with BRCAness rely on PARP1 and can be targeted by PARP inhibitors (PARPi)." (PMID 41057684, 2025). "The co-expression of HELLS and PARP1 in cancer might imply potential functional interactions between HELLS and PARP1." (PMID 41297801, 2025). "It has also been hypothesized that elevated levels of NNMT may promote cancer radioresistance by removing the inhibitory block of nicotinamide upon PARP-1, thereby enhancing DNA repair." (PMID 40497995, 2025). "These cancers might be less reliant on the enzymatic activity of PARP1, yet still respond to PARPi treatment at clinically relevant doses." (PMID 41459749, 2025). "Consequently, PARP2 does not play a role in the efficacy of olaparib and veliparib in BRCA1m cancer cells, it is entirely PARP1-dependent." (PMID 41459749, 2025). "The genetic interaction between PARP1 and the HRR pathway strongly supports that PARylation inhibition could play an important role in the efficacy of PARPi against HRR-deficient cancers." (PMID 41459749, 2025).
cancer (continued). "Likewise, our previous studies have demonstrated that PARP‐1 interacts physically with Ets‐1 and negatively regulates its level in cancer cells via PARylation." (PMID 39778077, 2025). "Therefore, the genetic vulnerability of cancer cells that harbor POLB polymorphism at dRP lyase domain or somatic mutation likely cause the perturbs the BER pathway and sensitizes cancer cells to PARP1 inhibitors." (PMID 41568291, 2025). "Contrarily, in cancer cells, PARP1 promotes glycolysis by activating HIF‐1α under hypoxia." (PMID 40904702, 2025). "Thus, PARP-1 inhibitors in single or combined therapy have been used in different types of cancer to eliminate this subpopulation of cells." (PMID 39858519, 2025). "Moreover, HMGA2 interacts with poly(ADP-ribose) polymerase 1 (PARP1) by enhancing PARP1 activity and reducing cancer cell sensitivity to olaparib (a PARP inhibitor)." (PMID 40475780, 2025). "Indeed, PARP‐1 regulates the transcriptional activity of many factors involved in cancer (e.g., Ets‐1)." (PMID 39778077, 2025). "Indeed, by inhibiting PARP1 and impairing a cell’s ability to repair single-strand DNA breaks (SSBs), PARPis took advantage of classical synthetic lethality in cancer treatment." (PMID 41273720, 2025). "Moreover, several studies have demonstrated that telomere replication and integrity are strongly connected to TARG1 activity on telomere pADPr catalyzed by PARP-1, highlighting its potential role in cancer cell signaling and survival." (PMID 41463260, 2025). "Interestingly, previous studies indicated that PARP-1 knockout mice were spared from inflammatory/autoimmune diseases or chronic infections involved in cancer development and progression." (PMID 40552150, 2025). "Furthermore, in these recurrent cancer cells, cisplatin and 5-fluorouracil have been shown to induce PARP1 gene expression." (PMID 40864763, 2025). "In addition, pamiparib traps PARP1/2 on damaged DNA, leading to the accumulation of double-strand breaks, which are particularly lethal to cancer cells with defective homologous recombination (HR) repair mechanisms." (PMID 40284519, 2025). "Furthermore, numerous studies have shown that PARP-1 expression is upregulated in cancer cell lines." (PMID 40577815, 2025). "Furthermore, through structure‐guided optimization, allosteric inhibitors can be engineered to shift from promoting release to enhancing retention, thereby conferring potent PARP1 trapping potency and increased cytotoxicity against cancer cells." (PMID 41473689, 2025). "While PARP1/2 inhibitors are widely used as a cancer therapy in the clinic, focus is shifting to the development of inhibitors for other PARPs are therapies for cancer and other diseases." (PMID 39969510, 2025). "PARP1, a nuclear enzyme involved in DNA repair and gene transcription, is present in a variety of tumor tissues and is targeted by inhibitors used for treatment of several cancer types such as ovarian, breast, pancreatic and prostate cancers." (PMID 41457066, 2025). "PARP1, the founding member, has received considerable research interest, in particular in cancer." (PMID 41468544, 2025). "Interestingly, precancerous lesions (e.g., severe dysplasia or carcinoma in situ) also exhibit high PARP1 expression levels." (PMID 40864763, 2025). "Thus, PARP1 overexpression promotes the upholding of the cancer integrity and its continued proliferation." (PMID 40149342, 2025). "The treatment landscape of BRCA-mutant cancers has been revolutionized by PARPi therapy and continues to improve with the development of more potent, PARP1-selective compounds that enhance tolerability and should facilitate exploration of combination therapies." (PMID 40460119, 2025). "Previously, reversal mutation of BRCA2, loss of PARP1 protein expression, and overexpression of drug efflux pumps ABCB1 (p‐glycoprotein) and ABCG2 (BCRP) have been linked to acquired resistance to PAPRi in BRCA2 mutant cancer." (PMID 40874518, 2025).
cancer (continued). "Moreover, MIF’s recruitment to DNA replication sites by PARP1(Poly(ADP-ribose) polymerase 1) during the S phase further emphasizes its involvement in maintaining cancer cell proliferation." (PMID 41159021, 2025). "We next assessed the contribution of PARP1 trapping towards PARPi activity in BRCA1m cancer cells." (PMID 41459749, 2025). "Considering the practical application value of PARPi in cancer therapy, we investigate whether any of the three newly identified PARP1 interactors could influence the efficacy of PARP inhibitors." (PMID 39174499, 2024). "Given that PARP1 inhibition can lead to synthetic lethality in cells with compromised homologous recombination, this enzyme has been identified as a potent target for anti-cancer therapeutics." (PMID 39695097, 2024). "The involvement of PARP1 in cancer development is well studied." (PMID 39456202, 2024). "The role of PARP1 in cancer has made it a significant target for therapeutic action." (PMID 39456202, 2024). "Notably, in the A2780 cancer cell line, this anti-proliferative effect is also accompanied by the induction of the apoptotic process, as evidenced by the activation of PARP1 cleavage and the downregulation of Bcl-XL protein." (PMID 39399313, 2024). "Inhibition of PARP1 results in the conversion of single-strand breaks into more severe double-strand breaks during replication, establishing a theoretical foundation for its role as a target in cancer therapy." (PMID 39474611, 2024). "Moreover, the correlation between PARP1 gene dependency and the sensitivity to the PARPi Talazoparib is very weak in most of the publicly available cancer cell lines." (PMID 39062190, 2024). "Notably, PARP1, a key protein in DNA damage repair and whose inhibitors are approved for various cancers, was previously shown to demonstrate enhanced interaction with SMAD4." (PMID 39528473, 2024). "PARP1 is best known for its clinical relevance in BRCA1-mutant cancers." (PMID 39730675, 2024). "Targeting UFMylation machinery through both replication fork stability and BER may present an alternative and promising approach for synthetic killing cancer cells by modulating PARP1 activity." (PMID 38657044, 2024). "Inhibition of the DNA repair protein PARP-1 is a promising concept in cancer therapy." (PMID 39456536, 2024). "Poly ADP-ribose polymerase 1 (PARP1) is an attractive therapeutic target for cancer treatment." (PMID 38582911, 2024). "Altogether, increasing the tumor mutational burden by PARP1 inhibition and mitochondrial deregulation could add CML to the cancer types that could benefit from immunotherapy." (PMID 38704604, 2024). "This could be one of the reasons why combined inhibition of Polθ with PARP1 or RAD52 kills cancer cells more effectively than inhibition of Polθ separately, while the effect of the treatment is less profound in normal cells." (PMID 39273083, 2024). "Here, we delineate the cellular consequences of XRN2 deficiency in cancer cells treated with clinically relevant PARP inhibitors (PARPi) to provide mechanistic insights into the synthetic lethal relationship between XRN2 and PARP1." (PMID 38339346, 2024). "Studies have shown that elevated levels of poly (ADP-ribose) are linked to a low infiltration of CD8+ cytotoxic T lymphocytes (CTLs), indicating that the activity of PARP1 might impact the interaction between cancer and the immune system." (PMID 38927911, 2024). "Conversely, PARP1 inhibition is a therapeutic approach against cancer." (PMID 39585988, 2024). "According to this concept, restraining PARP1 could be a latent therapeutic schedule for the therapy of cancers with defects in precise DNA repair genes, such as XRCC2, MRE11, and BRCA1/2." (PMID 38907095, 2024).
cancer (continued). "Herein, we revealed that TSA at a low concentration (1 μM) promoted the cisplatin-induced activation of caspase-3/6, which, in turn, increased the level of cleaved PARP1 and degraded lamin A&C, leading to more cisplatin-induced apoptosis and G2/M phase arrest of A549 cancer cells." (PMID 38893499, 2024). "PARP1 inhibitors for other cancers, such as HCC, are also being investigated in clinical trials." (PMID 38475878, 2024). "Therefore, there is a strong correlation between PARP-1 expression and metastasis, using patient samples in several cancer types." (PMID 39201718, 2024). "Thus, for the present study, the process that this model represents is the inhibition of PARP1 as a therapy for cancer." (PMID 38956095, 2024). "The cytoplasmic localization of PARP-1 has been reported in cancer cells." (PMID 38590714, 2024). "Inhibitors of PARP1 are widely used clinically in the treatment of cancers, including CRC." (PMID 38192816, 2024). "The expression of PARP-1 has been evaluated in several cancer types." (PMID 39201718, 2024). "Furthermore, PSIP1 depletion increases the sensitivity of cancer cells to PARP1 inhibitors and DNA-damaging agents that induce R-loop-induced DNA damage." (PMID 38191578, 2024). "It is therefore not surprising that PARP1-deficient mice were also reported to efficiently control the cancer growth of a breast tumor cell line." (PMID 39062190, 2024). "The formation of PARP1-DNA complex, which is trapped on the DNA, hinders the progression of replication fork and promotes DSB formation, which is the major mechanism by which PARPi kills HR-deficient cancer cells." (PMID 39156700, 2024). "Moreover, using the CCLE, we found that hematopoietic and lymphoid tissues cell lines present the highest PARP1 gene expression levels when compared to all other cancer (Wilcoxon test to the overall mean, p ≤ 2e-16)." (PMID 38704604, 2024). "Both situations limit cancer cell killing by restricting PARPi from trapping PARP-1 on damaged DNA." (PMID 38165032, 2024). "Finally, the PARP-1 inhibition and its effects on several cancer cell lines were evaluated for selected compounds." (PMID 38255943, 2024). "Compound 180055, as a PARP1 degrader, may address acquired resistance in BRCA-mutated cancers, which is often linked to restored BRCA function or activation of alternative DNA repair pathways." (PMID 39695097, 2024). "The detection of PARP-1 is necessary for early diagnosis of cancer and drug development." (PMID 38451295, 2024). "Moreover PARP-1 inhibitors such as Olaparib are commonly used in cancer treatment, confirming that PARP-1 inhibitors are good candidate for the treatment of diseases." (PMID 39353941, 2024). "The viability data suggest that compound 5 for the SH-SY5Y cell line and compounds 9 and 13 for the MCF7 cell line exhibit higher potential utility.These novel compounds hold promise as potential PARP-1 inhibitorsfor the development of targeted therapeutics against cancer." (PMID 39346823, 2024). "It has been well documented that PARP-1 is overexpressed in various carcinomas." (PMID 38255943, 2024). "Furthermore, PARP-1 inhibition leads to a significant decrease in the intravasation capacity of Erg-expressing cancer cells, which is more proof of the reduced ability of ETS-expressing cells to commit invasion under PARP-1 inhibition." (PMID 37686260, 2023). "One of the most discussed theories, explaining the Q/A-induced ATP depletion in cancer cells, particularly K3/A-treated and CoQ0-treated, attributes this effect to the activation of poly-[ADP ribose] polymerase 1 (PARP1) and inhibition of glycolysis, as a result of an acute depletion of NAD+." (PMID 37176145, 2023).
cancer (continued). "It has been documented that PARP1 can be regarded as a potential biomarker and therapeutic target for ischemic diseases, cardiac hypertrophy, diabetes, inflammation or neuronal death and some cancers (e.g., ovarian, breast and oral)." (PMID 37375313, 2023). "Poly (ADP-ribose) polymerase 1 (PARP1) is an enzyme that functions in DNA damage, repair, transcription, and, through regulation of cellular mitosis and processes such as apoptosis and necrosis, alters the life cycle of cancer cells." (PMID 37176092, 2023). "Additionally, PARP1 plays critical roles in cancer biology, including genome maintenance, replication, transcription, and chromatin remodeling." (PMID 37415147, 2023). "It has been suggested that the PARP2 function is not essential for antitumor activity in HRR-deficient cancer models, and that only PARP1 inhibition is required." (PMID 36994441, 2023). "All these findings indicated that compound 11b could provide new scaffolds for developing novel PARP-1 inhibitors applicable to cancer therapy." (PMID 37891641, 2023). "EVI1 and PARP1, part of TGF-ß pathway, are upregulated in cancers with DNA repair deficiencies with DNA repair deficiencies and may influce disease progression and survival." (PMID 37525239, 2023). "Additionally, anti-cancer therapeutics targeting PARP1 and PARP2 have been developed and are currently widely used in clinics." (PMID 36814782, 2023). "Here the authors show that DNA damage induced RNA m5C in R-loops competes with PARP1- mediated PARylation in transcribed genomes to promote cell survival which could be targeted be in cancer therapy." (PMID 37777505, 2023). "Together, these data indicate that drugs that target PARP1 and PARP2 may be clinically relevant for RB-deficient cancers." (PMID 37704395, 2023). "Pharmacological inhibition of PARP1 may kill those cancer cells that are undergoing constant endogenous DNA damage due to defects in DNA repair enzymes as well as cells that are being exposed to DNA damaging irradiation or cytotoxicants." (PMID 36743979, 2023). "Phosphorylation of PARP-1 at Y907 by the tyrosine kinase c-Met has been reported to increase PARP-1 catalytic activity and reduce the binding of PARPi, thereby causing PARPi resistance in cancer cells." (PMID 37609662, 2023). "Thus far, down-regulation of CDK12-dependent HR genes is being explored as an approach to eliminate cancer cells, most notably in combination with PARP1 inhibitors or DNA-damaging chemotherapeutics." (PMID 37811895, 2023). "Moreover, studies revealed that PARP-1 is meaningfully upregulated in many cancer cell lines and malignant tissues." (PMID 36835456, 2023). "Indeed, preclinical data have revealed that BRCA1/2-mutant cancer cells are sensitive to PARP-1 inhibition due to their dependence on PARP-1 activity for DNA (base excision) repair and, subsequently, survival." (PMID 37762072, 2023). "While PARP1 trapping and its cytotoxic effects are desirable in cancer treatment, this could be a limitation when planning to use PARPi in non-oncological conditions such as ischemia-reperfusion injury or neurodegenerative diseases." (PMID 37570820, 2023). "To further explore the involvement of the DDR proteins in the NORAD-mediated accumulation of γH2Ax we used siRNAs to KD two of the hits identified in the NORAD-associated proteome (LC-MS/MS experiment), namely PARP1 and CDK1, both proteins being extensively linked to cancer and DXR response." (PMID 37680988, 2023). "Moreover, PARPi enhance the binding strength between PARP1 and damaged DNA, inducing PARP1 trapping, which blocks the potential DNA repair pathway and ultimately kills cancer cells." (PMID 38047026, 2023). "As an essential marker of cancer treatment, PARP-1 inhibitors could effectively kill tumor cells through a mechanism known as synthetic lethality and are used to treat a variety of cancers." (PMID 37891641, 2023).